GATA4 (GATA binding protein 4)
Diseases named in the same sentence as GATA4 in open-access papers (continued):
Sharing a sentence is not in itself a finding about the gene and the disease.
cancer (continued). "RT-PCR analysis of β-catGOF; Mll1−/− organoids confirmed a decreased expression of Gata4 and revealed a concomitant upregulation of Bmp4 and the secretory differentiation markers Mmp7 and Muc2, identifying Mll1 as an upstream regulator of Gata4/Bmp4-controlled cancer stemness and differentiation." (PMID 33349639, 2020). "A potential explanation for this is that GATA4 is already gradually silenced in aged colon tissue as a result of age-associated promoter hypermethylation, with the aggravated hypermethylation in cancer not causing any further change in gene expression." (PMID 27562343, 2016). "For instance, GATA4 and GATA6 exert opposing effects in different cancers, which are influenced by chromatin remodeling and differential co-factor binding." (PMID 41514651, 2025). "This controversial function of master regulators like GATA4 and GATA6 in cancer, alongside their crucial functions in maintaining normal tissue balance, complicates efforts for their direct utilization in diagnosis or treatment." (PMID 39456519, 2024). "Aberrant expression of GATA4 and GATA6 contributes to cancer development, including GC, due to their critical role in physiological developmental processes." (PMID 39456519, 2024). "For instance, the TSS of several developmental-related and cluster 2 genes, such as GATA4, HOXD11, and HOXD12, was hypermethylated in a variety of cancer types." (PMID 35580989, 2022). "We found that CD44, CDK6, GATA4, GATA6, KLF5, and KRAS, which were amplified in TCGA STAD cohort, were amplified in cancer cell clusters." (PMID 35087207, 2022). "Differential hydroxymethylation is found in thousands of genes, most significantly in genes related to pancreas development or function (GATA4, GATA6, PROX1, ONECUT1, MEIS2), and cancer pathogenesis (YAP1, TEAD1, PROX1, IGF1)." (PMID 33077732, 2020). "We observed interesting relationships among the most methylated genes (TFPI2, SOX17, and GATA4) in OSCC cell lines and primary tumors in a cancer-specific manner." (PMID 31405379, 2019). "In previous studies, the reduction of GATA4 and GATA5 expression in various human cancers, including HCC, was shown to be due to gene promoter methylation in various human cancers, including HCC." (PMID 30672133, 2019). "Among the annotated AD versus NAT top50 hypermethylated DMRs, several markers were found to be hypermethylated in various cancers including FLI1, GATA4 and NGFR." (PMID 29945573, 2018). "In the present study, we showed that miR-200 suppresses BMP4 indirectly through the GATA4 and GATA6 transcription factors and that BMP4 knockdown inhibits cancer cell growth, migration, invasion, and metastasis." (PMID 26395571, 2015). "In the current study, we further analyzed the details of GATA4 and GATA6 expression in ovarian tissues and cancer, and examined the impact of the reduction of GATA6 in mice on ovarian surface epithelial transformation." (PMID 19649254, 2009). "When GATA4 was injected into cancer cells where it would not normally be present, it resulted in decreased cell growth and colony formation." (PMID 40699746, 2025). "The master regulatory role of GATA4 and GATA6 in organogenesis and cell specification, as well as their lineage survival nature, challenges the investigation of their broad function in gene-regulatory molecular pathways in cancer." (PMID 39456519, 2024). "While these studies focused on exploring the role of GATA4 in controlling proliferation, its role as a regulator of the pro-inflammatory secretome in cancer has not been extensively studied in vivo." (PMID 35017504, 2022).
cancer (continued). "Interestingly, all GATA family members besides GATA3 were mostly downregulated in most kinds of cancers, with upregulated vs downregulated study numbers (GATA1 1:7; GATA2 6:39; GATA3 31:36; GATA4 5:18; GATA5 1:17; GATA6 16:37)." (PMID 30872657, 2019). "This evidence, together with others showing the inverse correlation of GATA4 with GATA6 in many cancers, drives us to assume that GATA4 is no longer the protagonist as it behaved in hepatic development due to frequent loss of expression in adult liver tumors." (PMID 24498120, 2014). "Some cancer-related genes are located in these highly common, early appearing RARs: MCL1, CTSK, ARNT, S100A10, PTK2, PTP4A3, and PSCA in the RAR-Gs; and DLC1, PINX1, and GATA4 in the RAR-Ls." (PMID 22938721, 2012). "Furthermore, GATA-4, GATA-6 and Ihh expression is altered in premalignant dysplastic lesions and reduced in overt cancer." (PMID 18405344, 2008). "Additionally, it would be valuable to investigate whether other stimuli, such as hypoxia and starvation, also affect the ROS/GATA4/CLDN6 axis and whether there are variations in the response across various cancer cell types." (PMID 40959289, 2025). "Bisulfite sequencing analysis confirmed the cancer-specific methylation of the TFPI2, SOX17, and GATA4 promoters in the OSCC cell lines and tumors but not in the normal oral mucosa samples." (PMID 31405379, 2019). "With further development of antibodies and refinement of staining procedure, we carried out immunohistochemical analysis for the expression of GATA4 and GATA6 in a panel of ovarian non-neoplastic and cancer tissues in tissue microarray." (PMID 19649254, 2009). "GATA4 expression is reduced in some HOSE preparations and HIO lines, and is absent in all cancer lines as determined by both semi-quantitative RT-PCR and real-time RT-PCR." (PMID 19649254, 2009). "In the first example, GATA4 is already absent in the benign monolayer; GATA6 is positive in the monolayer cells but is lost in the adjacent cancer cells." (PMID 19649254, 2009).
heart disease (20 papers, 2010 to 2025). "We obtained a homology model for GATA4 from the Alphafold server to investigate the structural impact of missense mutations (F184S) on patients with heart disease." (PMID 39286212, 2024). "The method can readily be applied to other genetic variants in GATA4 or other genes in cardiac disease, providing a centralised assessment pathway for patient genetic variant interpretation." (PMID 38049901, 2023). "We investigated stem cell cardiac disease modelling and transcriptomics for the purpose of genetic variant classification using a GATA4 (p.Arg283Cys) VUS in a patient with CHD." (PMID 38049901, 2023). "Previous studies report that Gata4 and Gata6 are essential for heart development, and Hoxa1 mutant mice develop heart disease, suggesting a previously uncharacterized association between Hoxa1 and Gata4/6." (PMID 31147716, 2019). "However, most GATA4 pathogenic variants (31.82%) in patients with isolated cardiac diseases were located in transactivation domain 1 (TAD1), and only 9.09% of the variants were located in the N-ZF domain." (PMID 40290305, 2025). "Furthermore, we analyzed the data concerning GATA4 variants in patients with cardiac diseases alone, which were obtained from ClinVar." (PMID 40290305, 2025). "Finally, the study provides a disease appropriate model for the investigation of rare GATA4 genetic variants in patients with cardiac disease, or CHD." (PMID 38049901, 2023). "Many GATA4 mutations are associated with human diseases and exhibit impaired phosphorylation on S261 indicating that S261 phosphorylation defects are involved in human heart diseases." (PMID 34765091, 2021). "GATA4 also promotes cardiomyocyte survival by preventing apoptosis and regulating pathways involved in oxidative stress whereas mutations in GATA4 and Nkx2–5 have been implicated in heart disease, demonstrating the importance of these transcription factors in normal cardiac function." (PMID 25679215, 2015). "More evidence for the implication of GATA4 phosphorylation in cardiac diseases was provided in another study." (PMID 35563646, 2022). "In summary, cGMP-PKG signaling mediates the transcriptional activity of GATA4 connecting GATA4 and PKG-1α mutations with human heart disease." (PMID 34765091, 2021). "Molecular network analysis and protein–protein interaction study indicated FOXO1 as strong transcription factor which interacts with other key genes like GATA4, CITED and TBX5 located on different chromosomes but associated with lethal heart disorders in PS." (PMID 30423812, 2018). "Unlike the GATA4 variant loci identified in patients with 46,XY GD, only 9.09% of the GATA4 variants in patients with cardiac diseases alone were located in the N-ZF domain; moreover, most of the variants (31.82%) were located in TAD1." (PMID 40290305, 2025). "Taken together with the results of the naturally occurring mutant G296S, we suggest that disruption of the PGC-1α/ERR/GATA4 cooperative interaction could contribute to inherited and acquired human heart disease." (PMID 35418170, 2022). "As conclusion, a gene‐therapy approach to re‐express GATA4 or protein therapy with IL‐13 might be evaluated as therapeutic strategies to enhance myocardial regeneration in pediatric patients with heart disease or even in adult patients after MI in the future." (PMID 28053183, 2017). "If this is the case, enhancement of cardiac GATA4 levels or administration of IL‐13 might be evaluated as therapeutic strategy to improve myocardial regeneration in heart disease." (PMID 28053183, 2017). "For example, KLF13 is an important component of the transcription network required for heart development and suggests that KLF13 be a GATA-4 modifier, by analogy to other GATA-4 collaborators, mutations in KLF13 may be causative for congenital human heart disease." (PMID 26085920, 2015).
heart disease (continued). "Our study demonstrates GATA4 as an upstream regulator of CIP gene expression in cardiomyocytes, as well as the clinical significance of CIP expression in human heart disease." (PMID 35369338, 2022). "GATA4 variants in patients with 46,XY GD with/without CHD and patients with cardiac disease alone were also analyzed." (PMID 40290305, 2025). "Furthermore, we summarized the locations of GATA4 variants in patients with 46,XY GD with/without CHD and in patients with cardiac disease alone." (PMID 40290305, 2025).
infection (18 papers, 2013 to 2025). The state of being infected such as from the introduction of a foreign agent such as serum, vaccine, antigenic substance or organism. "We found that both EdU+ and Ki67+ cells were significantly decreased by Ad-Cre infection, compared with Ad-vector infection, indicating that cell proliferation rate is reduced by the loss of Gata4 in isolated cardiac fibroblasts." (PMID 37371122, 2023). "Adenovirus-mediated overexpression of Gata4 caused a marked reduction in laminin immunoreactivity, which further decreased as a multiplicity of infection (MOI) increased." (PMID 34699385, 2021). "We found that the transcription factor, GATA4, was highly regulated by Ad‐Zmiz1 infection in chondrocytes." (PMID 40040621, 2025). "We rarely observed Gata4 expressing cells with Ad-Cre infection, while most cells expressed Gata4 with Ad-vector infection." (PMID 37371122, 2023). "Through co-infection with the miR-199a-3p mimic and Ad-GATA4, it was confirmed that this approach led to the reduced anti-senescent effect of miR-199a-3p against Dox." (PMID 34864645, 2021). "Next, we knocked down GATA4 level using lentivirus-mediated infection with a specific shRNA and assessed FBP1 protein expression in DPSCs." (PMID 31892855, 2020). "Six inducing factors, Sry, Sox9, SF1, WT1, GATA4, and Dmrt1, were respectively transduced into mES cells by lentiviral infection according to the experimental design." (PMID 30850007, 2019). "Immunostaining and FACS analysis for ZIKV NS1 protein and the Sertoli cell marker GATA418 revealed that while >90% of the Sertoli cells were positive for GATA4, ~25–45% of the cells were positive for viral antigen 48 h post-infection." (PMID 29615760, 2018). "Only the Mef2c-Gata4-Tbx5 (MGT) and Mef2c-Tbx5-Gata4 (MTG) constructs, which have Mef2c in the first position, increase reprogramming efficiency compared to infection with three separate Gata4, Mef2c, and Tbx5 viruses." (PMID 28389873, 2017). "Subsequent to this, we induced GATA4 knockdown using lentivirus-mediated infection with a specific shRNA." (PMID 28484278, 2017). "To assess the function of GATA4 in SCAPs, we used lentivirus-mediated infection with a specific shRNA to knock down GATA4 expression." (PMID 28484278, 2017). "In the screening experiments following the infection of the fluorescent reporter cell population with activated GATA4 expression and an integrated dCas9-SAM system, we analyzed the gene expression differences between the EGFP-high cell population and the unsorted cell population." (PMID 40940741, 2025). "However, for MICFs, only about 0.1% cells were induced into cardiomyocyte-like cells after the infection of Gata4, Mef2c, and Tbx5." (PMID 33718351, 2021). "Among the GMT, Mef2c seems most rapidly targeted into nucleus, whereas Gata4 and Tbx5 were slower and observed in both the cytosol and nucleus by 3 hours of infection, however, by 4 hours of the infection time, most of injected proteins were localized into the nucleus." (PMID 26449528, 2015). "In our experimental conditions, the infection of RNVC with adMek1ca provokes a 60% decrease in Myh6, Mef2c, and Gata4 mRNA expression and a 40% decrease in Srf mRNA expression." (PMID 30206251, 2018). "At 6-weeks post-infection, ~15% of the Sertoli cells exhibited detectable ZIKV antigen of which ~90% were GATA4-positive." (PMID 29615760, 2018). "Then, we found that CGN, MAP3K5, GATA4 and RUNX1 related to tight junction were upregulated during DTMUV infection, indicating that these genes may play an important role in DTMUV entry." (PMID 35585616, 2022). "Histological evaluation using Sirius red revealed diminished fibrillar collagen deposition in the livers of mice injected with Ad-GATA4 compared with both control mice (no infection with adenoviruses) and mice injected with Ad-GFP." (PMID 34699385, 2021).
infection (continued). "Livers of CCl4-treated mice injected with Ad-GATA4 showed a decreased number of α-SMA–positive areas compared with both control mice (no infection with adenoviruses) and mice injected with Ad-GFP." (PMID 34699385, 2021). "mES cells with lentiviral transduction of all the six factors, Sry, Sox9, SF1, WT1, GATA4, and Dmrt1 (mES+Trans) had a relatively less growth rate as compared to those without infection (group mES+MEF and mES+TM4)." (PMID 30850007, 2019). "In line with the known immunomodulatory effects of H. pylori, the expression of CD-markers related to T helper (CD4/GATA4) and regulatory T cells (CD25/FOXP3) was suppressed upon an 11-month infection with H. pylori SS1, and this phenomenon was most pronounced in Cav1-KO mice." (PMID 23592983, 2013). "Although Gata4 seemed to be dispensable according to the number of mCherry+ cells, most of these cells tended to be round rather than spindle-shaped without Gata4 infection at a later stage." (PMID 33718351, 2021).
cardiovascular disease (7 papers, 2013 to 2025). "GATA4 played an important role in heart development, cardiomyocytes, and cardiovascular disease, and has been extensively studied." (PMID 35186035, 2022). "The finding also points to the possible involvement of yet undefined entities related to GATA4 transcription activity or gene regulatory pathways in events leading to these cardiovascular disorders." (PMID 24330461, 2013). "While the study has produced interesting data that may contribute to our knowledge of GATA4 interaction with cardiovascular disease, there are some limitations in the extent of its applicability." (PMID 24330461, 2013). "Thus, one of the main limitations is that no such potential mechanisms were tested to verify the notion that the 3′-UTR of the GATA4 gene plays an important role in the discussed cardiovascular disease pathways." (PMID 24330461, 2013). "For example, a BD-independent interaction between BRD4 and GATA4 has recently been reported to regulate the mitochondrial homeostasis in the adult heart, and the interaction interface is a potential target for pharmacological treatment of cardiovascular diseases." (PMID 40149571, 2025).
adenocarcinoma (4 papers, 2015 to 2023). A common cancer characterized by the presence of malignant glandular cells. "In fact, amplification of GATA4 and GATA6 is often found in adenocarcinomas from other origins." (PMID 26555375, 2015).
metabolic disease (2 papers, 2012 to 2013). A congenital disorder (due to inherited enzyme abnormality) or acquired (due to failure of a metabolically important organ) disorder resulting from an abnormal metabolic process. "Hence, the primary question raised in our study was whether a link existed between the impact of GATA4 on CAD manifestation and the presence of metabolic disorders, as our linkage study in HFH seemed to suggest." (PMID 24330461, 2013).
reproductive diseases (1 paper, 2017). "The expression pattern at rs12478601 (THADA locus) in skin and fat, rs804279 (GATA4 locus) and rs1795379 (KRR1 locus) in fat and rs2268361 (FSHR locus) in skin predicted involvement in reproductive diseases." (PMID 28068351, 2017).
GATA4 also shares sentences with these, for which no sentence is quoted: hypertrophy (8 papers); fibrosis (4); pulmonary atresia (4); age (3); anemia (3); autism (3); DiGeorge syndrome (3); Micropenis (3); Patent ductus arteriosus (3); Patent foramen ovale (3); atrial septal defect 2 (2); Cirrhosis (2); Frasier syndrome (2); gastrointestinal tumors (2); Insulin resistance (2); long QT syndrome (2); Lymph Node (2); metabolic syndrome (2); ovarian granulosa cell tumor (2); pancreatic adenocarcinoma (2); pancreatic ductal adenocarcinoma (2); type 1 diabetes (2); acute coronary syndrome (1); acute lymphocytic leukemia (1); acute myocardial infarction (1); acute promyelocytic leukemia (1); androgen resistance syndrome (1); atrial flutter (1); atrioventricular septal defect 4 (1); Atrophy (1).
A further 70 diseases each share a sentence with GATA4 in 1 paper.